CCND1 (cyclin D1)
Diseases named in the same sentence as CCND1 in open-access papers (continued):
Sharing a sentence is not in itself a finding about the gene and the disease.
cancer (continued). "Akt contributes to cancer cell survival and Akt/cyclin D1 signaling appears to promote HCC growth." (PMID 33902004, 2021). "In order to find the clinic correlation of cyclin D1 and reveal the mechanism of the genome-wide cyclin D1 binding sites and the changes of downstream genes in cancer, we firstly analyzed the correlation between cyclin D1 expression and prognosis in the tissue microarray (TMA) cohort." (PMID 34335935, 2021). "Besides, studies have confirmed that USP2 specifically deubiquitinates cyclin D1 through direct interaction, to regulate the growth of cancer cells." (PMID 33314748, 2021). "Most patients with KRAS-mutant cancers also have high cyclin D1 expression." (PMID 34830174, 2021). "This suggests that there are separate selective pressures for SHANK2 and Cyclin D1 amplification, and they may both promote cancer." (PMID 32661924, 2021). "The augmented activation of AKT by cyclin D1 may also drive glycolysis, as was observed in other cancer types." (PMID 33494394, 2021). "C-Myc and Cyclin D1 are target genes of Wnt/β-catenin signaling pathway and play a role in cell cycle progression, apoptosis, and may also regulate the sensitivity of cancer cells to chemotherapy." (PMID 33735820, 2021). "Indeed, while Cyclin D1 has been shown to be suppressed by PRMT5 inhibition in cancer cells, Cyclin D1 was unaffected by PRMT5 inhibitor treatment in untransformed Th cells, even though it is induced upon TCR stimulation." (PMID 34168658, 2021). "Moreover, miR-1 has been shown to promote tumorigenicity by upregulating Cyclin D1 (CCND1) gene expression, and miR-148a promotes cancer cell invasion and migration through the upregulation of Snail2." (PMID 33809601, 2021). "Besides, anoikis and anchorage-independent cell growth can be inhibited and activated, respectively, by cyclin D1 (CCND1) in cancer cells." (PMID 33435156, 2021). "Overexpression of cyclin D1 is often found in malignant neoplasms." (PMID 34830034, 2021). "Hence, silencing CCND1 gene can effectively suppress the cell cycle and apoptosis of cancer cells, which is in line with the results of a previous literature." (PMID 34806539, 2021). "The three clusters generated contained genes or proteins involved in apoptosis (BIRC3, BIRC5, PARP1, CASP8, and CASP9), transcriptional dysregulation in cancer (CDKN1B, RELA, CDKN1A, MYC, JUN, and MMP9), and cancer progression (CCND1, CASP3, CTNNB1, WNT1, and VEGFA) pathways." (PMID 34836311, 2021). "Cyclin D1 is often upregulated in cancer and a master regulator of G1 phase progression." (PMID 33673123, 2021). "Importantly, we demonstrate that the hAM homogenate affects the expression of cyclin D1 in cancer urothelial cells, as the expression is significantly diminished in the invasive cancer urothelial (T24) cells." (PMID 34249888, 2021). "Finally, together with the MAPK signaling pathway, it promotes the expression of CCND1, and then the proliferation of cancer cells was promoted." (PMID 33681289, 2021). "Fruther, cyclin D1 overexpression, as the one observed in alkylation resistant MED13 KO cells, was shown to be associated with chemo- or radiation- therapy resistance in cancers from patients." (PMID 33444446, 2021). "CCND1 overexpression leads to cell cycle changes and is noted in various types of cancers." (PMID 35011815, 2021). "The analysis showed the amplification of CCND1/CDK4/PLK1/CD44 based on percentages of separate genes, with 7% for CCND1, 2.9% for CDK4, 1.7% for PLK1, and 1.8% for CD44 in multiple cancers, including the missense mutation amplifications, deep deletions, and alteration frequencies of these oncogenes." (PMID 34063946, 2021). "Both cyclin-D1 inhibition and caspase-3 induction can inhibit cancer cell survival." (PMID 33946505, 2021).
cancer (continued). "Finally, we proposed in 2020 an overview of the role of autophagy, and namely its pivotal Beclin-1 protein, in CCND1 degradation, as a possibly actionable mechanism for G1/S cell cycle arrest in cancer." (PMID 34445095, 2021). "The CCND1 amplification is one of the major events observed in numerous human cancers." (PMID 33444446, 2021). "Furthermore, the FXR deficiency in a mouse model was correlated with an increase in inflammation and cancer cell proliferation by increasing the expressions of cyclin D1, β-catenin, c-Myc, and IL-6." (PMID 35006466, 2021). "Cyclin D1 is known as an oncogene and overexpressed in many kinds of cancers." (PMID 33128353, 2020). "Different from targeting CCND1 transcription or CDK4/6, antagonizing DILA1 may be an alternative or complementary way to downregulate Cyclin D1 protein in cancer treatment." (PMID 33139730, 2020). "It therefore appears that DHX9 may contribute to the overexpression of cyclin D1 in cancer following oncogenic EGFR upregulation, thus promoting proliferation and replicative immortality." (PMID 33437516, 2020). "The previous analytic results together with these reports indicated that hsa_circ_0088494-miR-876-3p might influence CTNNB1 and CCND1 expression and function, thereby exerting their roles in mediating cancer carcinogenesis and progression." (PMID 33363164, 2020). "Cyclin D1, a pivotal cell cycle regulator, promotes cell cycle progression in human cancer." (PMID 32296699, 2020). "Cordycepin restrains the proliferation of cancer cells by triggering adenosine A3 receptors followed by the Wnt signaling pathway, including glycogen synthase kinase three beta (GSK3β) activation and cyclin D1 inhibition." (PMID 33628175, 2020). "Assessing the contribution of each function of Cyclin D1 to cancer progression could contribute to develop therapies in an appropriately targeted and personalized manner." (PMID 33317149, 2020). "Some studies have shown that cyclin D1 can also support the migration and invasion of cancer cells." (PMID 32337233, 2020). "Although many F-box proteins contribute to the degradation of Snail, no concentration of mutations in specific regions of the protein is evident in cancer patients, unlike the situation for c-Myc and cyclin D1." (PMID 32429232, 2020). "Therefore, CCND1 is a candidate drug target for blocking the progression of cancer in CMS1 patients." (PMID 32548109, 2020). "Cyclin D1 antagonizes BRCA1-mediated repression of estrogen receptor α (ERα)–dependent gene expression suggesting that silencing of CCND1 combined with PARP inhibitors may lead to substantial benefit for several type of cancer patients." (PMID 33317149, 2020). "Amplification of the cyclin D1 gene and overexpression of cyclin D1 protein are frequently increased in many human malignancies to promote cancer cell proliferation indefinitely, while targeted restriction of the function of cyclin D1 can effectively inhibit the proliferation of cancer cells." (PMID 33014527, 2020). "We then further investigated the role of CCND1 amplification in specific cancer types." (PMID 32903763, 2020). "The overexpression of Cyclin D1 may, directly and indirectly, affect the other cellular processes, thus promote the development and progression of cancers." (PMID 32697404, 2020).
cancer (continued). "Reports show that over-expression of cyclin D1 and under-expression of tumour suppressor p21 is required for cancer initiation as it is confirmed that down-regulation of cyclin D1 and over-expression of p21 in xenograft model discontinues the formation of cancer in the early stages." (PMID 32807213, 2020). "Moreover, VEGFA, EGFR, CASP3, AKT1, and CCND1 were identified as hub genes in the antilung cancer of cinobufotalin injection." (PMID 32148531, 2020). "In particular, microRNA-16-5p modulates Cyclin D1/E1-pRb-E2F1 pathway in cancer cells." (PMID 31900225, 2020). "Furthermore, knockdown of cyclin D1 induced oxidative imbalance by elevating intracellular ROS levels in cancer cells, which promoted the senescence of cancer cells through a retinoblastoma-independent pro-senescence pathway." (PMID 31884567, 2020). "Increasing evidence indicates cyclin A2, cyclin D1 and cyclin E1 are positively correlated with the development of chemotherapy resistance, while the knockdown or depletion of these proteins inhibits cancer cell proliferation and promotes apoptosis, increasing sensitivity to chemotherapeutic drugs." (PMID 33292277, 2020). "Besides, many crucial genes related with cancer progression, such as Cyclin D1, c-Myc, and MMP9, are modulated by Wnt/β-catenin pathway." (PMID 31949128, 2020). "Three amplicons (KRAS, MAPK1, and CCND1) have been observed in cancer of oral cavity from Taiwanese patients, and therefore, all could possibly contribute to activation of EGFR signaling." (PMID 32974098, 2020). "We next analyzed cyclin D1 and c-myc expression levels in A549 and HCT116 cells to examine whether RPE affects the expression of proteins associated with cancer cell proliferation." (PMID 33158043, 2020). "Moreover, Zhang et al60 reported that knockdown cyclin D1 by siRNA strategy induces survivin reduction and cell death in cancer cells." (PMID 31821701, 2020). "The complex of CKD4 and CCND1 has been studied as a therapeutic target for cancer." (PMID 33679868, 2020). "Cordycepin exhibited an anti-cancer effect against B16 mouse melanoma by inducing the adenosine A3 receptor, and eventual activation of glycogen synthase kinase-3β, and the suppression of cyclin D1." (PMID 33628175, 2020). "Another study showed that cyclin D1 (encoded by CCND1) may play a key role in the maintenance of VEGFs, and antisense to cyclin D1 could be useful for targeting both cancer cells and blood vessels in tumors." (PMID 32903763, 2020). "Cyclin D1 controls many pathways in addition to the cell cycle, suggesting that the benefits of cyclin D1 inhibition in cancer may result from several mechanisms." (PMID 32928152, 2020). "Moreover, NF-kB stimulates the transcription of Cyclin D1, a key regulator of G1 checkpoint control of cell cycle, thus, contributing to cancer progression." (PMID 32824207, 2020). "Whether circ‐CCND1 also plays a similar regulatory role in other malignant tumours warrants further investigation." (PMID 31951319, 2020). "PKM2-dependent β-catenin transactivation regulates CCND1 expression and cell cycle in cancer cells." (PMID 33279948, 2020). "Activated STAT3 protein lead to the transcription of various downstream target genes such as IL-17, IL-23, BCL-XL, BCL-2, MCL1, cyclin D1 (CCDN1), c-MYC, and vascular endothelial growth factor (VEGF) that control essential pro-carcinogenic, inflammation-associated networks during cancer progression." (PMID 33584695, 2020). "One of the classic targets of Rsv in cancer cells is the cyclin D1/CDK4 complex." (PMID 33204396, 2020). "In addition to EMT activation, β-catenin, proliferation-related genes c-Myc and cyclin D1, and cancer stem cell marker Nanog were markedly upregulated in HCC cells exposed to CM from NE-treated LX2." (PMID 32293507, 2020).
cancer (continued). "Thus, it is noteworthy that ApoE knockout and knockdown led to decreased expression of cyclin D1 and its associated proteins CDK4 and CDK6, in urethane-induced lung tumors, lung metastases, and cancer cell lines." (PMID 31275318, 2019). "Further, we found that the expression level of cyclin D1 in EC tissues was higher than that in adjacent tissues, in which the enhancement of cyclin D1 expression was also identified in many different types of cancers." (PMID 31001342, 2019). "Furthermore, there is a growing evidence that has been reported that elevated cyclin D1 protein in cancers is a consequence of the defective proteasomal degradation pathway of cyclin D1 protein." (PMID 30736789, 2019). "In contrast, proteins that promote various cancer malignant properties, including CCND1, ERBB2, SNAIL, SLUG, phosphorylated STAT3 (p-STAT3), FAK, FOXM1, ETS1, YAP, HES1, and OCT4, were all significantly downregulated, an indication of reduction of malignancy in the cancer cells after EZH2 knockdown." (PMID 31130994, 2019). "In addition, MYC has also been connected to the CDK4/6 and that way to CCND1 through these cancer studies." (PMID 30976209, 2019). "A consistent downregulation of CHK1, CHK2, CDK6, and Cyclin D1 was observed, which confirms that cell cycle arrest at the G2/GM phase could be substantial for Lanatoside C treatment to cancer cells." (PMID 31783627, 2019). "Therefore, CCND1 was chosen for validation, because CCND1 is frequently reported to participate in the formation and progression of multiple human cancer types." (PMID 31434797, 2019). "When the canonical WNT pathway is upregulated as in cancers, the increase in β-catenin in the nucleus leads to activation of the expression of numerous genes, in particular CYCLIN D1 and cMYC, where the former influences the G1 phase of the cell division cycle, and the latter, the S phase." (PMID 31803621, 2019). "In addition, the activation of NF-κB associates with the upregulation of cell proliferation enhancers (e.g., cyclin D1 and c-myc), cell adhesion molecules, and several angiogenesis factors enhance cancer cell engraftment (e.g., ICAM-1 and VEGF)." (PMID 31163672, 2019). "In addition, the anti-cancer effect of ISO against invasive bladder cancer was reported through cyclin D1 inhibition." (PMID 31817453, 2019). "Interestingly, SOX9 has been reported to regulate β‐catenin expression positively in the canonical Wnt pathway and to influence the downstream effectors such as Cyclin D1 and c‐Myc to promote cancer progression." (PMID 31402556, 2019). "However, previous studies on cyclin D have focused on cyclin D1 because of its early discovery and widespread expression in human cancer compared with that of cyclins D2 and D3." (PMID 31511084, 2019). "Moreover, silencing of Akt1 and 2 isoforms was found to decrease the expression of proteins regulating cancer cell survival and proliferation such as cyclooxygenase-2, B-cell lymphoma 2 (Bcl-2), cyclin D1, and survivin." (PMID 31252679, 2019). "Another explanation of this observation is that CCND1 amplification might reflect general genomic instability in cancer cells, and such cells possess a more aggressive phenotype." (PMID 31159251, 2019). "This suggestion is consistent with previous observations indicating that elevated expression of both of these STAT proteins is seen in numerous cancers, where their phosphorylation results in enhanced expression of cell cycle progression (e.g., cyclin D1) and survival (e.g., Bcl-xL and Bcl-2) genes." (PMID 31291965, 2019). "Cyclin D1 amplification occurs in 58% of luminal B cancers and 29% of luminal A cancers." (PMID 31878959, 2019).
cancer (continued). "Pan‐Cancer Co‐Expression Analysis for the miRNA‐target interactions across 32 types of cancers from starBase V3.014 revealed that miR‐551b‐3p level was significantly inversely correlated with the level of CCND1 mRNA in CCA samples (r = −0.367, P = 0.0275)." (PMID 31199052, 2019). "Among them, both of CCNB1 and CCND1 are overexpressed in many cancers." (PMID 31592235, 2019). "Moreover, cyclin D1 can promote cancer formation and cancer survival through the regulation of transcription, DNA damage and repair, the induction of chromosomal instability as well as the enhancement of angiogenesis, cell migration and invasion." (PMID 31801187, 2019). "Our data demonstrate that cyclin D1 deficiency is a druggable vulnerability of SCCOHT, providing a rationale for a clinical trial using the available CDK4/6 inhibitors to treat this often-fatal cancer of young women." (PMID 30718512, 2019). "YBX1 has also been linked to the expression of other cancer-related genes (e.g., c-MYC, CCND1)." (PMID 31461477, 2019). "Moreover, a number of target genes of miR-155 affect other cancer-related processes, such as cell growth and survival (CCND1 and GAB3), cell adhesion junction (ANKRD6 and SMAD2), proliferation (SOCS1 and STAT3), and apoptosis (TP53BP1)." (PMID 31744065, 2019). "In the current study, we hypothesized that estrogen via ER activation in cSCC cells impacts cancer progression by modulating Cyclin D1 and CD55." (PMID 31611744, 2019). "Indeed, many phytochemicals with anti-cancer activity induced GSK3β-dependent cyclin D1 degradation." (PMID 30736789, 2019). "Numerous studies have demonstrated that cyclin D1 is closely related to cancers." (PMID 31583003, 2019). "IKKα plays a crucial role in NF-κB-cyclin D1-mediated proliferation of cancer cells." (PMID 31796128, 2019). "Therefore, overexpression of Cyclin D1 is frequently observed to promote cancer cell proliferation in a variety of cancers, including HCC." (PMID 31168049, 2019). "RRM2B may suppress cancer cell proliferation partially by upregulation of p21 and downregulation of cyclin D1 in addition to playing a critical role in DNA repair." (PMID 31637211, 2019). "Inhibition of cyclin D1 expression induced apoptosis of various cancer cells." (PMID 30736789, 2019). "PTEN, BRCA1, BRCA2, PI3K, and CCND1 genes were related to the BREAST cancer signaling pathway." (PMID 30792708, 2019). "To identify if hMSCs could affect cell cycles to promote cancer proliferation, we measured cyclin D1 level by western blotting and found the expression of cyclin D1 increased in HCC-hMSCs group." (PMID 31142737, 2019). "However, overexpression of Cyclin D1 in common cancers is believed to be a consequence of defective regulation at a posttranslational level." (PMID 31578445, 2019). "Moreover, it is known that the upregulation of Akt and NF-κB signaling pathways is related to the activation of cyclin D1 that leads to proliferation of cancer cells and decline in CDKI, p21, thus inhibiting apoptosis." (PMID 30275391, 2018). "CCND1 can have context-depending roles in vitro and in vivo: It is one of the major regulators of the cell-cycle progression, can act as an oncogene, and aberrant expression is commonly seen in human cancers." (PMID 29720725, 2018). "Moreover, the miR-302-367 cluster was reported to directly downregulate both AKT1 and cyclin D1, and indirectly upregulated p27Kip1 and p21Cip1, leading to the suppression of cancer cell proliferation, which is accordance with our data." (PMID 30326936, 2018). "Thus, cyclin D1 has been suggested to be one of the important targets for the anti-cancer drug development." (PMID 29554905, 2018). "The unique activity profile of tubacin identified here suggests that it may be effective as a therapeutic agent in not only FGFR3-dependent cancers, but other cancers in which cyclin D1 and/or MYC dysregulation are drivers." (PMID 29423038, 2018).